ADAR (adenosine deaminase RNA specific)
Diseases named in the same sentence as ADAR in open-access papers (continued):
Sharing a sentence is not in itself a finding about the gene and the disease.
cancer (continued). "The results of paired difference analysis in the TCGA cohort showed that ADAR was generally highly expressed across cancers." (PMID 37414093, 2023). "Given the significance of ADAR, we performed comprehensive bioinformatics analysis and in vitro experiments to explore the important role and special molecular mechanisms of ADAR across cancers." (PMID 37414093, 2023). "The expression of the adenosine-to-inosine (A-to-I) RNA-editing regulator ADAR was found altered in different types of cancer." (PMID 37958449, 2023). "Instead, we used the large number of independent samples to obtain as complete and authentic of a compendium of ADAR editing sites in a cancer cell line as possible." (PMID 37468903, 2023). "We hope that this study will provide new insights into improving the role of ADAR in cancer and tumor immunotherapy." (PMID 37414093, 2023). "On the other hand, the relationship between ADAR RNA editing and disease in humans, particularly cancer, represents an actively developing area of research." (PMID 37468903, 2023). "Accurate, long reads allow us to resolve full-length transcripts and RNA editing, equipping us to better understand the role of ADAR editing in the cancer transcriptome." (PMID 37398362, 2023). "We also found that the non-coding transcriptome represents the major reservoir of true ADAR editing events in a human cancer cell." (PMID 37468903, 2023). "Although the functions of ADAR in human cancers have been intensively studied, the specific roles and molecular mechanisms of ADAR in the tumor microenvironment and antitumor immunotherapy remain largely enigmatic." (PMID 37414093, 2023). "A previous study into RNA-edited hotspots in miRNAs across cancer types revealed 19 ADAR-dependent A-to-I RNA-editing hotspots in the mature sequence of miRNAs, including miR-3144-3p7." (PMID 36599932, 2023). "Meanwhile, ADAR was found to be positively correlated with the immune score and stromal score of some cancers, such as BLCA, COAD, HNSC, KIRC, OSCC, and PDAC." (PMID 37414093, 2023). "In other cancer types, ADAR suppression in ADAR-dependent cells triggers the production of type I IFNs and activation of the nucleic acid sensor PKR, a mediator of IFN-dependent growth arrest." (PMID 37024492, 2023). "Our results show that ADAR is positively correlated with the expression of chemokines, chemokine receptors, HLAs, and tumor necrosis factors (TNFs) in most cancers." (PMID 37414093, 2023). "In recent years, by regulating the global RNA editing level, research has increasingly indicated the therapeutic potential of ADAR-mediated RNA editing in treating human cancers." (PMID 38203521, 2023). "The documentation of these transcripts that are targets of ADAR and alternative splicing brings attention to further efforts to disentangle these regulatory processes involved in the cancer transcriptome." (PMID 37398362, 2023). "Abnormal expression of ADAR has been detected in numerous diseases, such as multiple autoimmune diseases and human cancers, and the abnormal expression of ADAR1/2 was positively correlated with the degree of RNA editing." (PMID 38203521, 2023). "ADAR enzymes can change the sequence, structure, and expression of several RNAs, affecting cancer cell behavior." (PMID 36009036, 2022). "Dysregulation of ADAR expression and ADAR‐mediated RNA editing has been shown to result in various diseases including cancer." (PMID 36221913, 2022). "To examine the role of ADAR, we identified AASE in 11 groups of ADAR knockdown (KD), knockout, or overexpression cancer cell lines." (PMID 35906682, 2022). "Different patterns of ADAR-mediated A-to-I mRNA editing in multiple types of cancer have been observed." (PMID 36476255, 2022). "In most cases, increased ADAR promotes cancer generation and progression; while in a few cancers, low expression and/or activity of ADAR mediates cancer phenotypes." (PMID 36499683, 2022).
cancer (continued). "Adenosine (A) to inosine (I) RNA editing catalyzed by adenosine deaminases acting on RNA (ADAR) enzymes is a post-transcriptional modification that emerged as a key player in tumorigenesis and cancer progression." (PMID 35365616, 2022). "Consistent with these important biological functions, alterations in ADAR expression and/or RNA editing occur in several human pathologies, including many cancers, autoimmune disorders, and neuropathological diseases." (PMID 35850307, 2022). "Our studies also suggest that oncogenic KRAS signaling is sufficient to induce at least a subset of the intrinsic ISG signatures that are observed across many cancers and cancer cells lines with ADAR dependencies." (PMID 35858545, 2022). "The imbalance of ADAR expression or activity can lead to a variety of diseases, such as cancer, Aicardi-Goutieres syndrome, and amyotrophic lateral sclerosis." (PMID 34616451, 2021). "Single-cell RNA analysis showed that ADAR was specifically upregulated in cancer cell clusters and was also expressed in stromal and immune cell clusters." (PMID 34616451, 2021). "We are looking forward to further report on the relationship between ADAR function in different cell types and cancers." (PMID 34616451, 2021). "ADAR dependency has been evaluated through large screening experiments and smaller studies involving knockdown or knockout of ADAR in panels of human cancer cell lines." (PMID 35586115, 2021). "First, only the expression and function of ADAR in BC cancer cells were verified, and the functions of ADAR in other cells such as immune cells and stromal cells were not studied." (PMID 34616451, 2021). "The importance of ADAR in tumor biology therefore makes it an ideal therapeutic target for multiple cancers." (PMID 35586115, 2021). "De-repressed irAlu expression led to ISG induction and sensitization of cancer cells to ADAR targeting." (PMID 34297039, 2021). "Widely reported as an oncogene in cancer, ADAR1 is a key member of the ADAR enzyme family that facilitates adenosine-to-inosine (A-to-I) editing in double-stranded RNA (dsRNA)." (PMID 33750389, 2021). "The innate immune response has been described as one of the main resistance mechanisms against resistance to ICB and the discovery of factors involved in reactivation of the innate response, such as ADAR, has been a priority for the cancer research community." (PMID 33214684, 2021). "Both 8-azaadenosine and 8-chloroadenosine show similar toxicity to ADAR-dependent and -independent cancer cell lines." (PMID 35586115, 2021). "We believe that, in different normal and cancer tissues, the balance between these two components (writers and erasers) can control ADAR1 protein level and the availability/editability of ADAR substrates." (PMID 33509238, 2021). "Accordingly, many cancer types such as liver and breast cancer as well as some gastrointestinal malignancies express high levels of ADAR, which also promotes cancer growth and metastasis." (PMID 33669629, 2021). "So far, many cancer cell lines have shown increased vulnerability toward type-I interferon signaling upon ablation of ADAR." (PMID 32728184, 2021). "TCGA portal was used to detect the expression of ADAR in cancer including BC, and its correlation with clinicopathological data as well as other genes was analyzed via UALCAN database." (PMID 34616451, 2021). "Since ADAR expression is often elevated in cancer, we assessed the cytotoxicity of 8-chloroadenosine and 8-azaadenosine in SK-BR-3 with or without overexpression of the p110 or p150 isoforms of ADAR." (PMID 35586115, 2021). "Several recent studies have highlighted the importance of ADAR expression in a wide range of cancer cell lines." (PMID 35586115, 2021). "In this review, we discuss the most recent findings concerning the role of microRNAs in triggering or exacerbating muscle wasting in cancer cachexia, while mentioning about possible roles played by long non-coding RNAs and ADAR-mediated miRNA modifications." (PMID 33330108, 2020).
cancer (continued). "Simultaneously, we provide some suggestions for ncRNA editing research and the potential application of ADAR inhibitors in the treatment of cancer." (PMID 33643923, 2020). "Although both ADAR and ADARB1 have been shown to play roles in tumorigenesis, most of cancer related editing events regulated by ADAR, primarily due to more abundant expression of ADAR and its unique features." (PMID 32410589, 2020). "The recent description of links between changes in ADAR function and disease––from neurological disease through to cancer––identifies new avenues for understanding how A-to-I modification of RNA can impact health and disease." (PMID 32603639, 2020). "ADAR frequently amplifies in human cancers consistent with the elevated expression and editing levels of its substrates." (PMID 32410589, 2020). "A further factor to consider in ADAR‐dependent cancer progression is the ADAR1 and ADAR2 RNA editing imbalances previously observed in cancer." (PMID 30802996, 2019). "In humans, three ADAR proteins (ADAR1–3) have been identified, and ADAR1 has been verified to play important roles in a variety of diseases, such as cancer and infection." (PMID 31315644, 2019). "Future directions include establishing the deaminase content of EVs extruded from M2 TAMS66, 67 and establishing the dynamic role of active APOBEC (and ADAR) heterodimer genetic markers as common and dominant features predicting cancer progression." (PMID 30802996, 2019). "Whole transcriptome RNA variant analyses have shown that adenosine deaminases acting on RNA (ADAR) enzymes modify a large proportion of cellular RNAs, contributing to transcriptome diversity and cancer evolution." (PMID 30290838, 2018). "Here, through analysis of genome-scale loss-of-function datasets, we identify adenosine deaminase acting on RNA (ADAR or ADAR1) as an essential gene for the survival of a subset of cancer cell lines." (PMID 30575730, 2018). "We observed similar results in an extended panel of ADAR KO-insensitive cancer cell lines treated with IFN-β, although the magnitude of the cell lethality phenotype varied between cell lines." (PMID 30575730, 2018). "In summary, ADAR enzymes seem to have both anti-tumoral or a pro-tumoral effect in different types of cancer by reducing the expression of onco-miRs or tumor suppressors miRs." (PMID 30018188, 2018). "In human cancers, the normalized editing levels were found to be correlated to ADAR gene expression." (PMID 29363428, 2018). "In contrast, two of the five cancer types with significantly increased AZIN1 editing showed a significantly decreased expression of ADAR in tumor samples." (PMID 26980570, 2016). "Recent evidence indicates that ADAR-directed RNA editing represents a novel mechanism of disease progression and a promising therapeutic target for diverse human cancers." (PMID 25889244, 2015). "We found a significant correlation (P-value = 2.38 ×10−7 by Wilcoxon rank sum test) between the number of A:T>G:C events and ADAR expression levels, implying the existence of new cancer subtypes determined by the amount of somatic RNA-editing." (PMID 25526364, 2014). "Indeed, two adenosine analogs, 8-azaadenosine and 8-chloroadenosine, have been claimed as effective ADAR inhibitors, with several studies reporting their anti-proliferative effects on various cancer cell types." (PMID 41608661, 2026). "Second, we have turned to study the extent by which endogenous-ADAR may potentially be harnessed for cancer treatment." (PMID 40330550, 2025). "ADAR has recently been shown to modulate the interaction between the tumor and the adaptive immune system, which is relevant to the cancer setting." (PMID 40852728, 2025). "The “RNA Tether Model” of Michael R Lieber and colleagues fundamentally enhances our understanding of the mechanism of “off-target RT Ig-SHM like” processes consistent with our general model of dysregulated AID/APOBEC and ADAR driven RT Ig-SHM like mutagenesis across the cancer genome." (PMID 39940758, 2025).
cancer (continued). "In addition to regulating the physiological functions of normal cells, ADAR has also been shown to play a role in regulating the initiation and progression of several malignant tumors." (PMID 40936898, 2025). "Additionally, alterations in expression levels for ADAR (the A-to-I RNA-editing regulator) have been observed across different types of cancer." (PMID 40175891, 2025). "In addition, it was indicated that ADAR regulates its own expression by self-editing, and also affects the global transcription and translation products of cancer-related genes by editing and changing their expression profiles." (PMID 40351534, 2025). "If reverting just one driver mutation per tumor has a clinical impact, our results suggest that more than a third of cancer patients may be suitable candidates for endogenous-ADAR therapy." (PMID 40330550, 2025). "Due to ADAR involvement in protein diversity and gene expression regulation, when ADAR editing or ADAR expression is dysregulated, this can lead to cancer promotion or the downregulation of tumor suppressor pathways, making ADAR1 and ADAR2 appealing drug targets for oncology." (PMID 40362314, 2025). "Considering the successful application of lipid-nanoparticles (LNPs) as therapeutic agents in different cancer types, the prospects of delivering endogenous-ADAR to various cancers seem promising, as it requires the insertion of only a small payload containing a gRNA into the cell." (PMID 40330550, 2025). "Therapeutic targeting of the adenosine deaminase ADAR has great potential in cancer and other indications; however, it remains unclear what approach can enable effective and selective therapeutic inhibition." (PMID 39992915, 2025). "ADAR proteins are involved in a multitude of broader mechanisms that influence cancer." (PMID 40362314, 2025). "The dual role of ADAR in regulating tumor progression in different cancers suggests that ADAR’s regulation of downstream signaling pathways may be tissue-specific." (PMID 40936898, 2025). "Rather than using adjuvants (Azacitidine, for example) to increase the already significant levels of dsRNA in cancer cells, pathways that clear dsRNA (ADAR, PNPase, or autophagy) could be targeted." (PMID 38334619, 2024). "Therefore, further understanding of the role of ADAR enzymes and RNA editing in cancer is crucial for developing new cancer treatment strategies." (PMID 39091293, 2024). "Likewise, the combined impact of the DRR-ADARB1/ADAR/A3F mutations and age-A1 mRNA levels was also seen for indel signatures ID1, ID2, and ID7 in pancancer analyses as well as in certain cancers." (PMID 38965255, 2024). "Different cancer types exhibit varying levels of ADAR enzyme expression and RNA editing." (PMID 39091293, 2024). "In addition, the UALCAN database was used to study the differences in ADAR protein levels between cancer and normal tissues in multiple cancers." (PMID 37414093, 2023). "The finding from the expression levels of ADAR mRNA showed statistically significant upregulated expressions in pan-cancer databases compared with control (P < 0.0001), especially CRC, which was extracted from TCGA CRC dataset, CPTAC protein, and Human Protein Atlas (HPA) databases." (PMID 36660243, 2023). "Dysregulated ADAR-mediated RNA editing and RNA splicing are both commonly observed in many cancers." (PMID 38203521, 2023). "Subsequently, we generated a dot plot of ADAR gene alterations across cancers." (PMID 37414093, 2023). "Interestingly, we found that ADAR was a cancer essential gene in CRC, according to gene effect scores derived from CRISPR knockout screens published by Broad's Achilles and Sanger's SCORE projects." (PMID 36660243, 2023). "In this study, we systematically elucidated the integrated landscape of ADAR in cancer." (PMID 37414093, 2023).
cancer (continued). "We explored the immune cell infiltration landscape of cancer samples with the highest ADAR expression (TCGA-FD-A3SR-01, TCGA−FD−A3SR−01, TCGA−GC−A3RB−01) and the lowest ADAR expression (TCGA-CF-A3MI-01, TCGA−CF−A47T−01, and TCGA−ZF−A9R4−01) in TCGA-BLCA using the Timer 2.0 database." (PMID 37414093, 2023). "Inhibiting ADAR can help prevent cancer cells from becoming resistant to anti-tumor drugs." (PMID 38203521, 2023). "We observed the genetic alteration status of ADAR across cancers through the cBioPortal database." (PMID 37414093, 2023). "Based on these clues, we comprehensively explored the expression of ADAR across cancers." (PMID 37414093, 2023). "ADAR mRNA was elevated and was a cancer essential gene in CRC." (PMID 36660243, 2023). "In particular, ADAR was found to be a target for cancer immunotherapy." (PMID 35865544, 2022). "We propose that complete or partial inhibition of ADAR may enhance the proapoptotic and cytotoxic effects of splicing inhibitors and that it may be considered a promising addition to cancer therapies targeting RNA splicing." (PMID 35563631, 2022). "To explore the relationship between LGP2 and ADAR1 and its prognostic value for overall patient survival, we performed in silico analysis of ADAR1 and LGP2 (encoded by ADAR and DHX58, respectively) mRNA expression in multiple cancer types using data from The Cancer Genome Atlas (TCGA)." (PMID 35156720, 2022). "Additionally, recent studies underlined the essential role of epitranscriptomic mechanisms in cancer, such as A-to-I RNA editing mediated by the active ADAR enzymes (ADAR1–2)." (PMID 36009036, 2022). "Interestingly, in this research, single-cell analysis showed that ADAR was specifically upregulated in cancer cell clusters and was also expressed in stromal cells (such as fibroblasts) and immune cells (such as macrophages)." (PMID 34616451, 2021). "Knockdown or knockout of ADAR causes reduced proliferation and increased cell death in numerous, but not all cancer cell lines." (PMID 35586115, 2021). "In this study, we simply verified the function of ADAR in cancer cells." (PMID 34616451, 2021). "A-to-I RNA editing (ADAR) is a recently described epigenetic modification that may contribute to human cancer onset." (PMID 33671588, 2021). "In most types of cancer, the activity of ADAR enzymes is significantly decreased, as witnessed by the extensive hypoediting of Alu RNAs, as well as by the reduced expression of ADAR enzymes." (PMID 34282776, 2021). "As such, inhibition of ADAR function is a viable therapeutic strategy for many cancers." (PMID 35586115, 2021). "However, there is increasing evidence that the dysregulation of RNA editing central mediators (such as ADAR) contributes to the progression of cancer." (PMID 34899345, 2021). "Additionally, ADAR enzymes modify a large proportion of cellular RNAs, contributing to transcriptome diversity and cancer evolution." (PMID 33802575, 2021). "This is the first report of ADAR expression in various cell clusters for cancer research." (PMID 34616451, 2021). "Editing sites may serve as biomarkers for cancer and ADAR enzymes are considered as promising gene therapy agents to fight cancer." (PMID 34367244, 2021). "Like METTL3 enzyme, also the ADAR proteins have been indicated as an important player in cancer." (PMID 33509238, 2021). "Through a series of bioinformatic predictions and specific cell experiments, this study explored the expression of ADAR in BC, especially in cancer cell populations, its clinical relevance, possible molecular mechanisms, and its relationship with the tumor microenvironment." (PMID 34616451, 2021). "Our study indicates that, for an anti-cancer ADAR-mediated therapy, it could be more efficient to target ADAR1 protein than its deaminase activity." (PMID 33509238, 2021). "Besides redirecting events, ADAR-mediated impairment of miRNA biogenesis also contributes to cancer biology." (PMID 33916692, 2021).